CENPF (centromere protein F)
Diseases named in the same sentence as CENPF in open-access papers (continued):
Sharing a sentence is not in itself a finding about the gene and the disease.
ciliopathy (14 papers, 2015 to 2024). A genetic disorder of the cellular cilia or the cilia anchoring structures, the basal bodies, or of ciliary function. "In line with the extensive phenotypic heterogeneity documented in many ciliopathies and in Strømme syndrome, the severity of the disease varies remarkably as illustrated in this report, although all have CENPF null alleles." (PMID 38002928, 2023). "Not surprisingly, the clinical presentation of Strømme syndrome due to loss of CENPF function overlaps with both ciliopathies and disorders caused by defects in centrosomal and microtubule‐regulating genes." (PMID 35488810, 2022). "A previous study identified compound heterozygous variants in CENPF, leading to truncated proteins, in patients with ciliopathy and microcephaly phenotypes." (PMID 30477169, 2018). "This includes examples of clinicopathological overlap between ciliopathy and microcephaly patients, as well as mutations in the microtubule-regulating protein CENPF that are associated with both ciliopathy and microcephaly disorders." (PMID 27335639, 2016). "Our data identify CENPF as a new centriolar disease gene implicated in severe human ciliopathy and microcephaly related phenotypes." (PMID 25564561, 2015). "In the current study, we identify CENPF, the MT-regulating gene, as a new centriolar disease gene implicated in severe human ciliopathy and MCPH-related phenotypes." (PMID 25564561, 2015). "The kinetochore protein, CENPF, is mutated in human ciliopathy and microcephaly phenotypes." (PMID 27738186, 2016). "Based on CENPF’s intracellular localization and on the presence of ciliopathy phenotypes in zebrafish cenpf morphants, Strømme syndrome was concluded to be a primary ciliopathy." (PMID 38002928, 2023). "For most proteins, the trend reflected results from the WCP (i.e. PLK4 is up‐, whereas CEP63 and CEP57 down‐regulated) with the ciliopathy‐associated proteins CEP41 and CENPF being notable exceptions." (PMID 31304626, 2019).
lung adenocarcinoma (13 papers, 2008 to 2025). A carcinoma that arises from the lung and is characterized by the presence of malignant glandular epithelial cells. "CENPF expression has been related to lung adenocarcinoma progression through the regulation of the ERβ2/5 signaling pathway and the PI3K–AKT–mTORC1 signaling pathway." (PMID 36661515, 2023). "It is worth noting that through somatic mutation analysis, we found that AURKB, CDC20, CENPF, and KNTC1 had different frequencies of mutations in patients with lung adenocarcinoma, and mainly missense mutation type." (PMID 35354488, 2022). "Somatic mutation analysis showed that AURKB, CDC20, CENPF, and KNTC1 had different types of mutations in patients with lung adenocarcinoma, and the main type was missense mutation." (PMID 35354488, 2022). "With the GEO database analysis, Human centromere protein F (CENPF) is highly expressed in lung adenocarcinoma (LUAD), and the co-expression of CENPF and ERβ was found in the nucleus of LUAD cells through immunofluorescence." (PMID 33428600, 2021). "Also, knockdown of CENPF can inhibit the progression of lung adenocarcinoma by suppressing the expression of ER2/5 of the ERβ2/5 pathway." (PMID 36644760, 2022). "Knockdown of CENPF could inhibit the progression of lung adenocarcinoma by suppressing the ERβ2/5 pathway." (PMID 35141213, 2021). "Previous results have demonstrated that CENPF was highly expressed in the lung adenocarcinoma (LUAD), and CENPF expression correlated with T stage and poor prognosis." (PMID 39922805, 2025).
microcephaly (11 papers, 2015 to 2025). A congenital or acquired developmental disorder in which the circumference of the head is smaller than normal for the person's age and sex. "Biallelic loss‐of‐function (LoF) variants in CENPF gene are responsible for Strømme syndrome, a condition presenting with intestinal atresia, anterior ocular chamber anomalies, and microcephaly." (PMID 35488810, 2022). "In fact, previous studies identified that depletion of CENPF resulted in mitotic delay and mutations within the gene have been linked to microcephaly." (PMID 29036922, 2017). "In a second unrelated patient exhibiting microcephaly, we identified two CENPF mutations [c.1744G>T, p.E582X; c.8692 C>T, p.R2898X] by whole exome sequencing." (PMID 25564561, 2015). "To date, biallelic truncating variants in CENPF have been identified in eight patients and six fetuses with clinical features of Strømme syndrome but also in one child with nonsyndromic microcephaly and learning disability." (PMID 35488810, 2022). "Similarly, our cohort of cases with biallelic CENPF variants suggests that CENPF defects might be associated with ID, microcephaly, and dysmorphic features even in the absence of the typical malformations of Strømme syndrome (i.e., anterior chamber malformation of the eye and intestinal atresia)." (PMID 35488810, 2022).
nasopharyngeal carcinoma (11 papers, 2010 to 2024). A carcinoma arising from the nasopharyngeal epithelium. "In addition, another study showed that the expression of BUB1B and CENPF were up-regulated in nasopharyngeal carcinoma and their high expression was associated with poor OS." (PMID 30393234, 2019). "Our recent cDNA microarray data showed that centromere protein F (CENP-F) is significantly upregulated in primary cultured nasopharyngeal carcinoma (NPC) tumor cells compared with normal nasopharyngeal epithelial cells." (PMID 20828406, 2010). "The product of CENPF may play a role in chromosome segregation during mitosis and can be used as a valuable marker of nasopharyngeal carcinoma progression." (PMID 21799901, 2011).
bladder cancer (10 papers, 2017 to 2025). "Meanwhile CCNB1, CENPF and BUB1B genes were revealed to be positively co-expressed with ANLN in bladder cancer from three different datasets." (PMID 28600503, 2017). "Levels of CDCA3, CENPF, CENPA and KIF4A are correlated in bladder cancer." (PMID 34905505, 2021).
colorectal cancer (10 papers, 2012 to 2025). A primary or metastatic malignant neoplasm that affects the colon or rectum. "The migration and invasion assays showed that knocking down CENPF significantly weakened the ability of colorectal cancer cell migration and invasion." (PMID 39922805, 2025). "In TCGA, we observed that the expression of CENPF mRNA is significantly elevated in colorectal cancer and rectal cancer, similar to many other broad-spectrum tumors, compared to adjacent normal tissues." (PMID 39922805, 2025). "Overall, these findings showed that CENPF can enhance the migration, and invasion of colorectal cancer cells in vitro." (PMID 39922805, 2025). "However, we also found that CENPF transcription levels are abnormally elevated in colorectal cancer." (PMID 39922805, 2025). "Moreover, leveraging data from GEO, TCGA databases, and our own colorectal cancer tissue microarrays from two different centers, we explored CENPF expression patterns and prognostic significance in CRC." (PMID 39922805, 2025). "Thus, we speculate that CENPF is a key downstream target of USP4 in regulating colorectal cancer metastasis." (PMID 39922805, 2025). "A recent study illustrated that serum CENPF antibody could predict clinical response to infliximab in rheumatoid arthritis patients, and it further demonstrated potential diagnostic value for early stage HCC and colorectal cancer." (PMID 35059422, 2021). "In particular, MYC, MAD2L1, CENPF, UBE2C, NUF2 and NCAPG2 were identified as highly expressed in colorectal cancer samples." (PMID 38637125, 2024). "The core genes, namely MYC, MAD2L1, CENPF, UBE2C, NUF2 and NCAPG2, showed elevated expression in colorectal cancer samples, in stark contrast to their comparatively lower expression in normal samples." (PMID 38637125, 2024). "Importantly, the interaction of CENPF and USP4 then controlled the invasion and migration of colorectal cancer." (PMID 39922805, 2025). "Notably, the core genes (MYC, MAD2L1, CENPF, UBE2C, NUF2, NCAPG2) had differential expression in colorectal cancer samples in comparison to normal samples." (PMID 38637125, 2024).
glioma (9 papers, 2012 to 2026). A benign or malignant brain and spinal cord tumor that arises from glial cells (astrocytes, oligodendrocytes, ependymal cells). "CENPF, TOP2A, UBE2C, PBK, and MKI67 were strongly expressed in glioma clusters, indicating the presence of progenitor cells." (PMID 39333557, 2024). "In addition, we found several hub genes with worse OS and higher expression level in glioma patients, including VEGFA, NDC80, TIMP1, SAA1, CENPA, CENPF, and NCAPG and we firstly found relationship of SAA1, TIMP1, and molecular pathology in GBM." (PMID 30867991, 2019).
melanoma (9 papers, 2016 to 2025). A malignant, usually aggressive tumor composed of atypical, neoplastic melanocytes. "In conclusion, CENPF was significantly upregulated in melanoma and was associated with a worse prognosis in melanoma." (PMID 40299364, 2025). "We showed that CENPF was upregulated in melanoma and associated with a poor prognosis." (PMID 40299364, 2025). "Firstly, we verified that CENPF mRNA and protein expression was upregulated in melanoma tissues compared to normal tissues, and patients with a high level of CENPF had a poorer prognosis than those with a low level of CENPF." (PMID 40299364, 2025). "In general, these results suggested that CENPF facilitated melanoma progression through promoting cell proliferation, inhibiting cell apoptosis and influencing melanoma’s immune properties." (PMID 40299364, 2025). "Based on the promoting effect of CENPF in melanoma development, we further explored the mechanisms of CENPF’s upregulation in melanoma cells." (PMID 40299364, 2025). "We found that CENPF, E2F3, KIRREL, METRN were both upregulated and associated with worse OS in melanoma patients." (PMID 40299364, 2025). "This study aimed to investigate the clinical significance, biological function, and regulatory mechanisms of CENPF in melanoma." (PMID 40299364, 2025). "To investigate the mechanism of CENPF in melanoma proliferation, we performed flow cytometric analysis." (PMID 40299364, 2025). "Knockdown of CENPF suppressed melanoma cell proliferation, migration, and invasion in vitro, while inducing G2/M phase arrest and apoptosis." (PMID 40299364, 2025). "CENPF expression was validated in clinical samples (n = 128), melanoma cell lines, and xenograft models." (PMID 40299364, 2025). "Our previous study using scRNA-seq data revealed a subset of melanoma cells with high proliferative ability, with CENPF being the top differential gene." (PMID 40299364, 2025). "In conclusion, these results indicated that knockdown of CENPF arrested melanoma cells in G2/M phase and increased cell apoptosis." (PMID 40299364, 2025). "Taken together, our results show that CENPF is a novel prognostic biomarker and potential therapeutic target for melanoma treatment." (PMID 40299364, 2025). "Concerning the miR-383-5p/CENPF pathway, low miR-383-5p expression and overexpression of CENPF in melanoma cells led to increased proliferation and migration." (PMID 36313570, 2022). "MiR-383-5p directly targets CENPF mRNA; therefore, miR-383-5p acts as a tumor inhibitor in melanoma." (PMID 36313570, 2022). "Excitingly, both CENPF staining and EdU incorporation were markedly reduced in the melanoma sections incubated with the Pin1-FOXM1-blocking peptides." (PMID 26279295, 2016). "Compared with neonatal human epidermal melanocytes, BRAFV600E-mutated Colo829 human melanoma cells showed enhanced expression of Pin1, FOXM1, CENPF and Cyclin B1 both at the mRNA and protein levels." (PMID 26279295, 2016). "In conclusion, we identified the E2F3–CENPF axis in melanoma, which contributes to melanoma’s high proliferative ability, and demonstrated that knocking down CENPF could inhibit melanoma cell proliferation and induce cell apoptosis." (PMID 40299364, 2025). "Therefore, we further aimed to determine the role of CENPF in melanoma’s high proliferation ability." (PMID 40299364, 2025). "Moreover, the GSE75356 profile, which contained the RNA sequencing data of eight melanoma cell lines and one human normal melanocyte line, showed that CENPF was significantly upregulated in all the melanoma cell lines." (PMID 40299364, 2025). "Besides, in our previous study, single-cell RNA sequencing revealed a subset of melanoma cells of high proliferation ability, with CENPF being the top differentially expressed gene." (PMID 40299364, 2025).
melanoma (continued). "Taken together, these results indicated that CENPF could promote the proliferation and inhibit metastasis of melanoma cells in vitro." (PMID 40299364, 2025). "All of these lines of evidence indicate that CENPF may play an important role in melanoma progression." (PMID 40299364, 2025). "In summary, these results indicated that CENPF knockdown could inhibit melanoma growth and metastasis in vivo." (PMID 40299364, 2025). "Centromere protein F (CENPF), a mitotic regulator, has been implicated in tumor progression, but its role in melanoma remains unclear." (PMID 40299364, 2025). "In melanoma, a study showed that CENPF was an independent prognostic and metastasis biomarker, and upregulated CENPF might lead to premature depletion of CD4+ memory T cells and immunosuppression." (PMID 40299364, 2025). "Similarly, in our clinical specimens, CENPF’s mRNA level was found to be increased in 11/12 melanoma tissues compared with peritumor tissues." (PMID 40299364, 2025). "In melanoma cells, miR-383-5p overexpression suppressed CENPF expression." (PMID 36313570, 2022). "Importantly, CENPF expression was elevated in the same area, indicating that in the Pin1-positive melanoma FOXM1 signaling is active." (PMID 26279295, 2016). "Additionally, increased expression of CENPF may lead to the premature exhaustion of CD4+ memory T cells and immunosuppression, and has been linked to worse prognosis in melanoma patients." (PMID 39766071, 2024). "Increased expression of CENPF results in early exhaustion and immune suppression of CD4 + T cells, suggesting its potential as a predictive indicator for melanoma spread and a target for treatment." (PMID 38097686, 2023). "Similar to the human and mouse melanoma samples and the MEF samples, Pin1 and CENPF co-expressed in individual Colo829 cells." (PMID 26279295, 2016). "Firstly, we detected the expression of CENPF in five melanoma cell lines (SK-MEL-28, A2058, SK-MEL-2, MV3, and A375) by qRT-PCR and chose SK-MEL-28 and A2058 cells, which had the highest expression of CENPF for further experiments." (PMID 40299364, 2025). "Univariate analyses showed that CENPF could be an independent prognostic factor for both OS and DFS in melanoma patients." (PMID 40299364, 2025). "In order to elucidate the potential pathway of CENPF’s function in melanoma, we further analyzed the TCGA SKCM datasets, in which the 10% of samples that had the lowest CENPF expression were categorized as CENPF-low and the highest 10% were categorized as CENPF-high." (PMID 40299364, 2025). "Individual melanomas from independent data sets showed that FOXM1, CENPF and Cyclin B1, but not actin (control), significantly correlated with Pin1 expression." (PMID 26279295, 2016).
osteosarcoma (9 papers, 2018 to 2023). A usually aggressive malignant bone-forming mesenchymal neoplasm, predominantly affecting adolescents and young adults. "However, there are still some limitations in the present study, in vivo studies are needed to clarify osteosarcoma cell apoptosis and proliferation caused by CENPF resulting from XBP1 and ATF6 signaling pathway." (PMID 32973403, 2020). "The purpose of the present study is to elaborate a possible mechanism, which brings about the changes of CENPF expression through an ER stress-mediated manner in human osteosarcoma cells." (PMID 32973403, 2020). "In this study, we demonstrated that ER stress plays a crucial role in regulating CENPF transcription and protein expression in human osteosarcoma cells." (PMID 32973403, 2020). "Accordingly, we examined the effect of 3 different ER stress inducers on the regulation of CENPF mRNA and protein levels in different osteosarcoma cell lines." (PMID 32973403, 2020). "CENPF plays a key role in the regulation of the cell cycle, of which the levels contributed to increased cell proliferation by mediating apoptosis and cell cycle in osteosarcoma with a poor prognosis of osteosarcoma." (PMID 36482360, 2022). "Our findings may help to achieve a better understanding of CENPF expression regulation in osteosarcoma progression." (PMID 32973403, 2020). "Eight out of the 54 hub‐genes (ASPM, CENPF, KIF14, KIF20A, RCC1, SMC2, SRC, and TOP2A) were significantly decreased after NACT (criteria: |fold change| ≥ 2 and adjusted p value < 0.05), consistent with the central role of these hub genes in osteosarcoma." (PMID 37457661, 2023). "IGFBP5 has been identified as a hub gene in osteosarcoma along with origin recognition complex subunit 6 (ORC6), minichromosome maintenance 10 replication initiation factor (MCM10), MET proto-oncogene, receptor tyrosine kinase (MET) and centromere protein F (CENPF)." (PMID 36465383, 2022).
pancreatic cancer (9 papers, 2017 to 2025). "Also, CENPF is markedly elevated in pancreatic cancer (PC) and linked to poor patient outcomes." (PMID 39922805, 2025).
liver cancer (8 papers, 2012 to 2025). An epithelial or non-epithelial malignant neoplasm that arises from the liver. "Then, immunohistochemistry staining validated from the Human Protein Atlas database showed that ZWINT, NCAPG and CENPF protein expression were strongly upregulated in liver cancer tissues compared with normal tissues." (PMID 31410310, 2019). "On average, the CENPF gene was amplified in 22.9% of cancer cell lines, and showed a particularly high amplification frequency in liver cancer cell lines (50%; n = 7/14)." (PMID 22912832, 2012). "Overexpression of CENPF promotes the EMT process of liver cancer cells." (PMID 35796646, 2023). "Finally, survival analysis, based on clinical information from the TCGA-liver cancer datasets, revealed that the high expression of EZH2, GINS1, and TPX2 correlated positively with higher risk, CENPF and BUB1B were quite the contrary." (PMID 30100882, 2018). "Among them, TOP2A, CENPF, MEFV and C9orf72 directly affect the prognosis of patients with liver cancer." (PMID 38017425, 2023). "TOP2A, CENPF, ACSL4, SPARC, and COL4A5 were significantly upregulated in patients with liver cancer, while they were downregulated by CTD treatment in HCC cells." (PMID 38017425, 2023). "We found that 5.0 fold and 3.4 fold increases of CENPF and GMNN gene expression were observed in liver cancer tissues, respectively." (PMID 22912832, 2012). "Therefore, MAPT, TOP2A, CENPF and MEFV were identified as hub genes of CTD targets that regulate autophagy and also sever as oncogenes or tumour suppressor genes to affect the prognosis of patients with liver cancer." (PMID 38017425, 2023).